SH3GLB2 (SH3 domain containing GRB2 like, endophilin B2)
Synonyms: KIAA1848; PP6569; PP9455; RRIG1
Tractability: PROTAC: ubiquitination databases record sites on it; its protein half-life has been measured.
Gene: Protein-coding gene on chromosome 9 (129,007,036 to 129,028,369, reverse strand). Ensembl gene ENSG00000148341.
Subcellular location: Cytoplasm
Subcellular location (Human Protein Atlas): Cytosol; Nucleoplasm
Gene Ontology:
Molecular function: cadherin binding; identical protein binding; protein binding; protein-macromolecule adaptor activity
Biological process: endocytosis; membrane organization
Cellular component: cytoplasm; cytosol; membrane
Genetic constraint (gnomAD): Loss-of-function variants: 24 observed, 42.94 expected, observed/expected ratio (o/e) 0.56, 90% interval 0.4 to 0.79. The upper end of that interval is the gene's LOEUF score, 0.79, which puts it in group 3 of 6, group 1 being the genes least tolerant of losing a copy. Missense variants: 425 observed, 478.1 expected, observed/expected ratio (o/e) 0.89, 90% interval 0.82 to 0.96. Synonymous variants: 227 observed, 196.62 expected, observed/expected ratio (o/e) 1.15, 90% interval 1.03 to 1.29.
Homologues: Orthologues: chimpanzee SH3GLB2 (99% identical), pig SH3GLB2 (97% identical), dog SH3GLB2 (97% identical), mouse Sh3glb2 (97% identical), rat Sh3glb2 (96% identical), macaque SH3GLB2 (95% identical), chimpanzee SH3GLB2 (94% identical), guinea pig SH3GLB2 (94% identical), rabbit SH3GLB2 (86% identical), tropical clawed frog sh3glb2 (80% identical), zebrafish sh3glb2b (75% identical), zebrafish sh3glb2a (73% identical), and 3 more. Paralogues in human: SH3GLB1 (60% identical), SH3GL1 (26% identical), SH3GL2 (24% identical), SH3GL3 (24% identical), SH3RF3 (17% identical), SORBS1 (17% identical), SH3RF1 (16% identical), SH3D19 (15% identical), SORBS2 (15% identical), SORBS3 (13% identical), SH3RF2 (12% identical), NCF4 (11% identical).
Diseases named in the same sentence as SH3GLB2 in open-access papers:
SH3GLB2 is named in the same sentence as 15 diseases in open-access papers, as found by Europe PMC text mining. Sharing a sentence is not in itself a finding about the gene and the disease. The quoted sentences say what the papers report.
Alzheimer disease (2 papers, 2018 to 2022). A progressive, neurodegenerative disease characterized by loss of function and death of nerve cells in several areas of the brain leading to loss of cognitive function such as memory and language. "Zfra restores memory deficits in Alzheimer’s disease triple-transgenic mice by blocking the aggregation of TPC6AΔ, SH3GLB2, Tau, and amyloid β, and reducing inflammatory NF-κB activation." (PMID 30158849, 2018).
esophageal cancer (1 paper, 2011). A primary or metastatic malignant neoplasm involving the esophagus. "Moreover, our study also revealed that these two genes were differentially expressed in esophageal and prostate cancer cell lines and that benzo[a]pyrene diol epoxide (BPDE) reduced RRIG1 expression but did not alter SH3GLB2 mRNA levels in esophageal cancer cell lines (our unpublished data)." (PMID 21266059, 2011).
neuroblastoma (1 paper, 2022). Neuroblastoma (NB) is the most common solid, extracranial childhood tumor. "The second important finding is that as an inducer of PD, neurotoxin MPP+ rapidly increases WWOX phosphorylation at Tyr33 and upregulates the expression of TPC6AΔ, followed by TIAF1, SH3GLB2, Aβ, and tau in neuroblastoma SK-N-SH cells." (PMID 36498839, 2022). "By treating neuroblastoma SK-N-SH cells with neurotoxin MPP+, upregulation and aggregation of TPC6AΔ, along with aggregation of TIAF1, SH3GLB2, Aβ, and tau occurred." (PMID 36498839, 2022). "Here, by treating neuroblastoma SK-N-SH cells with neurotoxin MPP+, upregulation and aggregation of TPC6AΔ, along with aggregation of TIAF1, SH3GLB2, Aβ, and tau, occurred." (PMID 36498839, 2022).
oral cancers (1 paper, 2025). "Additionally, down-regulation of cytoskeletal proteins, including SH3GLB2 (endophilin-B2), spectrin (SPTAN1), and annexin (ANXA2) in T2D individuals mirrors the pattern seen in oral cancers and precancerous lesions." (PMID 39794871, 2025).
SH3GLB2 also shares sentences with these, for which no sentence is quoted: breast carcinoma (1 paper); cancer (1); ductal carcinoma in situ (1); endometriosis (1); influenza infection (1); invasive breast carcinoma (1); lymph node metastasis (1); melanoma (1); prostatic cancer (1); tumor (1); viral infection (1).